NSD1 (nuclear receptor binding SET domain protein 1)
Diseases named in the same sentence as NSD1 in open-access papers (continued):
Sharing a sentence is not in itself a finding about the gene and the disease.
Sotos syndrome (continued). "Analysis of genome-wide DNA methylation of SOTOS syndrome patients revealed a highly specific signature able to differentiate patients with pathogenic NSD1 mutations from controls, benign NSD1 variants and clinically overlapping syndromes." (PMID 34575025, 2021). "This is clearly shown by the variants of NSD1 in cases 1 and 2, who were later assigned as affected by Sotos syndrome, and the variants identified in ERF, FGFR1, and FGFR3, all genes associated with craniosynostosis and, rather frequently, Chiari malformation." (PMID 33337535, 2021). "Pseudoacromegaly has also been described in patients suffering from Sotos syndrome resulting from pathogenic variants in the NSD1 gene." (PMID 33210059, 2020). "A 2-year-old female was diagnosed with Sotos syndrome after genetic analysis demonstrating NSD1 mutation and 5Q35 microdeletion and she was under follow-up since birth." (PMID 32331522, 2020). "Sotos syndrome is an autosomal dominant disorder caused by mutations in the nuclear receptor SET domain-containing protein 1 (NSD1) gene located on 5q35." (PMID 33194904, 2020). "Variant rs28580074 (NSD1) is prevalent in Weaver syndrome and Sotos syndrome according to NCBI ClinVar." (PMID 32708070, 2020). "In approximately 90% of the patients, Sotos syndrome is associated with mutations in NSD 1 (nuclear receptor SET domain-containing protein 1) gene, protein insufficiency and a 5q35 microdeletion." (PMID 32331522, 2020). "The identification of a patient with an NSD1 mutation, which is associated with Sotos syndrome, is of particular interest since previous case reports suggest adnexal tumors in some patients with this condition." (PMID 31101826, 2019). "We first analyzed the data from individuals with Sotos syndrome, a congenital overgrowth syndrome that results from mutation of the epigenetic modifier NSD1, a lysine histone methyltransferase." (PMID 31160375, 2019). "NSD1-associated Sotos syndrome presents with overgrowth as the main phenotype during the first years of life, with distinctive facial traits and developmental delays characterized by intellectual disability." (PMID 31998360, 2019). "Germline inactivating mutations in NSD1 are responsible for Sotos syndrome, a childhood overgrowth condition in which patients are at increased risk of cancer and display an NSD1 mutation-specific DNA methylation signature." (PMID 31321084, 2019). "Sotos syndrome is caused by loss-of-function mutations in the NSD1 gene, which encodes a histone H3 lysine 36 (H3K36) methyltransferase." (PMID 31409373, 2019). "The diagnosis of Sotos syndrome relied solely on these clinical criteria until haploinsufficiency of the NSD1 gene was identified as causative." (PMID 31470900, 2019). "Sotos syndrome is caused by loss-of-function heterozygous mutations in the NSD1 gene, a histone H3K36 methyltransferase." (PMID 31409373, 2019). "Of interest, we also found a hypomethylated region in the promoter of the NSD1 gene (mutations of which lead to Sotos syndrome) in patients with Claes-Jensen syndrome." (PMID 29456765, 2018). "Overall, this analysis indicates similarity between the hypomethylation signatures associated with NSD1 inactivation in cancer and Sotos syndrome." (PMID 29213088, 2017). "Haploinsufficiency of the NSD1 (nuclear receptor binding SET domain protein 1) gene was first identified as the primary cause of Sotos syndrome in 2002." (PMID 27771801, 2017). "Using germline DNA from Sotos syndrome patients, it has been shown that loss of NSD1 function is associated with extensive DNA hypomethylation." (PMID 29176703, 2017). "To formally test effect of NSD1 inactivation on the Sotos syndrome overlap index, we combined NSD1 mutations and deletions into a single ‘NSD1 lesion score’ and tested for a linear association between this score and the Sotos syndrome overlap index." (PMID 29213088, 2017).
Sotos syndrome (continued). "As the majority of cases of Sotos syndrome are caused by abnormality of the NSD1 gene, our findings provide further evidence to suggest a possible genetic mechanism associated with ASD." (PMID 27771801, 2017). "Sotos syndrome is an overgrowth syndrome with intellectual disability caused by haploinsufficiency of the nuclear receptor binding SET domain protein 1 (NSD1) gene, an HMTase at 5q35.2–35.3." (PMID 27834868, 2016). "In particular, partial or whole NSD1 gene 5q35 microdeletions are the most common cause of Sotos syndrome in Japanese patients." (PMID 27834868, 2016). "It has since been suggested that mutations of the NSD1 gene are responsible for approximately 90% of cases of Sotos syndrome." (PMID 26872390, 2016). "We mapped previously identified mutations in NSD1 from Sotos syndrome patient samples to MMSET in attempt to identify important domains that are required for proper function of the two proteins." (PMID 25188243, 2014). "Deletions and point mutations of the NSD1 gene cause Sotos syndrome with cerebral gigantism, overgrowth and macrocephaly." (PMID 23342975, 2013). "The diagnosis of Sotos syndrome relied solely on clinical criteria until haploinsufficiency of the NSD1 gene (encoding a histone methyltransferase implicated in chromatin regulation) was identified as causative." (PMID 22926222, 2012). "Clinically, Weaver syndrome is closely related to Sotos syndrome, which is frequently caused by mutations in NSD1." (PMID 22287508, 2012). "Weaver syndrome shares many clinical similarities with the overgrowth condition, Sotos syndrome, which is due to mutations in the histone methyltransferase NSD1." (PMID 22190405, 2011). "Sotos syndrome is caused by haploinsufficiency of the NSD1 (nuclear receptor binding SET domain protein 1) gene, which encodes a coregulator of nuclear receptors that can activate or repress transcription." (PMID 18001468, 2007). "Screening of the NSD1 gene in a cohort of 88 familial and sporadic cases of autism and macrocephaly did not reveal any intragenic mutations or deletions, indicating that Sotos syndrome is a rare cause of autism spectrum disorders." (PMID 18001468, 2007). "In contrast, NSD1 microdeletions are the primary cause of Sotos syndrome in Japan, accounting for over 50% of cases." (PMID 17825104, 2007). "Our results suggest that Sotos syndrome is a rare cause of autism spectrum disorders and that screening for NSD1 mutations and deletions in patients with autism and macrocephaly is not warranted in the absence of other features of Sotos syndrome." (PMID 18001468, 2007). "NSD1 intragenic mutations cause 60% to 80% of Sotos syndromes cases in Europe and USA, whereas 5q35 microdeletions encompassing NSD1 cause ~ 10% of cases." (PMID 17825104, 2007). "The evaluation of the tumor frequency in patients with NSD1 anomalies will be important to further define the tumor risk in patients with Sotos syndrome." (PMID 17825104, 2007). "In the two patients with the NSD1 variant, the hypothesis of Sotos syndrome was in fact raised before the genetic test, clinically, based on the fully consistent phenotype of generalised overgrowth and the typical facial and hands characteristics." (PMID 40282429, 2025). "Sotos syndrome is a childhood overgrowth syndrome caused by haploinsufficiency of the NSD1 gene." (PMID 40766782, 2025). "Interestingly, submicroscopic deletions involving the entire NSD1 gene are the major causes of Sotos syndrome in Japanese patients, accounting for more than 50% of the subjects." (PMID 38535015, 2024). "Sotos syndrome is caused by deletions or intragenic variants in NSD1 gene located on chromosome 5." (PMID 39425694, 2024). "In summary, the identification of a novel de novo NSD1 likely pathogenic variant in our patient expands both the mutation and phenotype spectrum associated with Sotos Syndrome, thereby providing valuable insights into the potential mechanism underlying of pinealoblastoma pathology." (PMID 38459438, 2024).
Sotos syndrome (continued). "The aim of our study was to analyze the prevalence of HD, the anatomic types, and the genetic characteristics of 45 patients with Sotos syndrome carrying pathogenetic variants of NSD1 or a 5q35 deletion encompassing NSD1, who were followed at Bambino Gesù Children’s Hospital in Rome." (PMID 38535015, 2024). "Sotos syndrome (SS) is an overgrowth disease characterized by distinctive facial features, advanced bone age, macrocephaly, and developmental delay is associated with alterations in the NSD1 gene." (PMID 37908045, 2023). "Haploinsufficiency of the NSD1 gene is the main cause of Sotos syndrome." (PMID 37908045, 2023). "Sotos syndrome is an autosomal dominant genetic disorder caused by mutations in the NSD1 gene." (PMID 37508608, 2023). "Characteristics of Sotos syndrome caused by alterations of NSD1 gene." (PMID 37908045, 2023). "Cells derived from a patient with Soto’s syndrome hosting an NSD1-inactivating mutation was shown to have a global redistribution of the DNA methyltransferase DNMT3A, along with promoter DNA hypomethylation, dysregulated synapse formation, and dysregulated neurodevelopmental gene expression." (PMID 35581654, 2022). "Sotos syndrome is usually caused by haploinsufficiency of NSD1 located on 5q353." (PMID 36379925, 2022). "Soto’s syndrome, which occurs in 1/14,000 births and is associated with intellectual disability, facial deformation, and overgrowth phenotypes, is genetically mapped to NSD1 haploinsufficiency." (PMID 35581654, 2022). "Revealing the function of NSD1 in chondrogenic differentiation and bone growth is helpful to understand the overgrowth of Sotos syndrome patients with NSD1 mutations and to expand our understanding of the function of epigenetic regulation in chondrogenesis and skeletal biology." (PMID 34099628, 2021). "Interestingly, ccRCC with epigenetic NSD1 silencing displayed a specific genome-wide methylome signature consistent with the NSD1 mutation methylome signature observed in SOTOS syndrome." (PMID 34575025, 2021). "Mutations in the nuclear receptor-binding SET domain protein 1 (NSD1; OMIM #606681) were found to be causal for Sotos syndrome and mutations of NSD1 may account for more than 75% of the reported cases." (PMID 33488679, 2020). "Similarly, a unique methylation epi-signature has been reported for Sotos syndrome, caused by mutations in the NSD1 gene, which encodes histone H3 lysine 36 methyltransferase." (PMID 29456765, 2018). "To test the significance of overlap between the hypomethylated CpG signatures associated with NSD1 inactivation in cancer and Sotos syndrome, we calculated an index of overlap between the Sotos syndrome hypomethylated CpG signature and cancer hypomethylated CpGs in each patient." (PMID 29213088, 2017). "Initially, NSD1 mutations were found to lead to the Sotos syndrome." (PMID 29156722, 2017). "Moreover, a DNA hypomethylation signature has been reported in Sotos syndrome, a monogenic disorder defined by germline NSD1 mutations." (PMID 28405244, 2017). "Chromosomal microdeletions involving the NSD1 gene have been described as a major cause of Sotos syndrome in Japanese patients (prevalence >45%), but are less frequently found in non-Japanese patients (approximately 10% of prevalence), where intragenic point mutations are highly prevalent." (PMID 27834868, 2016). "NSD1 mutations are found in 70%–93% of classical cases of Sotos syndrome, but the molecular basis is unknown for remaining patients." (PMID 27834868, 2016). "To date, over 400 different mutations in NSD1 associated with Sotos syndrome have been reported." (PMID 27834868, 2016). "Although the presence of the three major criteria and several other conditions associated with Sotos syndrome allow us to infer a clinical diagnosis of typical Sotos syndrome, the genetic analysis of the NSD1 gene is considered another criterion for the confirmation of the molecular diagnosis." (PMID 27834868, 2016).
Sotos syndrome (continued). "Interestingly, a methylome study on patients with Sotos syndrome observed very pronounced demethylation in the NSD1-mutated group." (PMID 26464434, 2016). "NSD1 alterations have been associated with Sotos syndrome, a syndrome of childhood overgrowth." (PMID 27213592, 2016). "Our findings indicate that PHD domains are additional regions of MMSET that may be considered as therapeutic targets and suggest how these point mutations may inactivate NSD1 in Sotos syndrome." (PMID 25188243, 2014). "Notably, haploinsufficiency of the histone methyltransferase NSD1 causes the Sotos syndrome, that is characterized by very high stature and the gene can be inactivated epigenetically in tumors." (PMID 24963031, 2014). "The most common mutation (50%) was a micro deletion of the 5q35 region including NSD1 in Japanese patients with Sotos syndrome, while, in the UK, approximately 70% of patients with Soto syndrome have NSD1 point mutations, and only 10% of the patients have a micro deletion of the 5q35 region." (PMID 21549014, 2011). "Additionally, germline mutations that result in full gene inactivation are predominantly truncating mutations that occur throughout the gene, for example NSD1 mutations in the overgrowth condition, Sotos syndrome." (PMID 22190405, 2011). "It has been proposed that NSD1 may cause other overgrowth phenotypes, such as Weaver syndrome, Sotos syndrome, and BWS." (PMID 20407649, 2009). "Fifteen familial cases of Sotos syndrome have been reported with NSD1 mutations." (PMID 17825104, 2007). "Sotos syndrome is an overgrowth syndrome characterized by macrocephaly, advanced bone age, characteristic facial features, and learning disabilities, caused by mutations or deletions of the NSD1 gene, located at 5q35." (PMID 18001468, 2007). "Sotos syndrome is an autosomal dominant condition characterized by overgrowth with advanced bone age, macrodolicocephaly, motor developmental delays and learning difficulties, and characteristic facial features caused by heterozygous pathogenetic variants in the NSD1 gene located on chromosome 5q35." (PMID 38535015, 2024). "NSD1 is a chromatin modifier that suggests that the selection could influence brain development during modern human evolution and is not present in other primates; however, nowadays the nucleotide diversity is associated with Sotos syndrome." (PMID 36550402, 2022). "We conclude that chromatin modifiers like NSD1 could influence brain development during human evolution and are not present in other primates, and nowadays the nucleotide diversity is associated with Sotos syndrome." (PMID 36550402, 2022). "In addition, these findings suggest that the Sotos syndrome mutations in NSD1 may have similar consequences, rendering the enzyme incapable of regulating chromatin structure and gene expression." (PMID 25188243, 2014). "However, several familial cases of Sotos syndrome with NSD1 mutations have been described in the past years, suggesting that familial, usually milder, forms of the disorder might be underdiagnosed." (PMID 18001468, 2007). "We then compared the DNAm profiles for the three familial NSD1 exon 3 deletion cases to the confirmed cases of Sotos syndrome (n = 8) and control samples (n = 64)." (PMID 41153407, 2025). "DNA hypomethylation was also apparent in the three family members with the NSD1 exon 3 deletion with the proband being most similar to the episignature observed in confirmed Sotos syndrome patients." (PMID 41153407, 2025). "Patients with the Sotos syndrome phenotype carrying a 5q35 deletion encompassing the NSD1 gene have also been reported in about 5–20% of Caucasian patients." (PMID 38535015, 2024). "In 2015, we identified a DNA methylation signature for Sotos syndrome (MIM: 117,550) caused by pathogenic variants in the epigenetic regulatory gene, NSD1 [MIM:606681] (Nuclear Receptor Binding SET Domain Protein 1)." (PMID 37022461, 2024).
Sotos syndrome (continued). "The Sotos syndrome is an autosomal dominant disorder characterized by haploinsufficiency of NSD1 gene, with some individuals affected by epilepsy and, rarely, drug-resistant seizures." (PMID 36970544, 2023). "The phenotypes of Sotos syndrome and the functional domains of NSD1 protein were summarized by literature reviewing." (PMID 37908045, 2023). "Analysis of homozygous Nsd1 mutant embryos at embryonic day 9.5 showed they had a smaller prosencephalon which was unexpected based on the human clinical findings on Sotos syndrome." (PMID 36845425, 2023). "Epigenetic age acceleration has previously been reported in Sotos syndrome and Tatton-Brown-Rahman syndrome (TBRS), which are caused by loss of function variants in two genes encoding epigenetic regulators, NSD1 and DNMT3A, respectively." (PMID 35361921, 2022). "Later on, Visser and collaborators performed a comprehensive study on dermal fibroblasts from patients with Sotos syndrome to decipher the molecular mechanisms of NSD1 functions." (PMID 36230787, 2022). "In line with that, Choufani and collaborators showed that NSD1′s haploinsufficiency triggers a specific genome-wide pattern of DNA methylation alterations, which might represent a highly sensitive and robust diagnostic tool for Sotos syndrome compared to other overgrowth development syndromes." (PMID 36230787, 2022). "Although NSD1′s alterations have primarily been incriminated in the overgrowth Sotos syndrome, additional NSD1 disruption have been depicted in other developmental syndromes." (PMID 36230787, 2022). "Previous genetic investigations, including array CGH, screening for Sotos syndrome (NSD1) and Cowden syndrome (PTEN), intellectual disability panel, and trio ES, had returned normal results." (PMID 36393831, 2022). "An increasing amount of evidence indicates the critical role of the NSD1 gene in Sotos syndrome (SoS), a rare genetic disease, and in tumors." (PMID 35888078, 2022). "One of NSD1′s potential downstream effectors in Sotos syndrome is Adenomatous polyposis coli 2 (APC2), a tumor suppressor gene involved in the negative regulation of the Wnt/β-catenin signaling pathway." (PMID 36230787, 2022). "It is worth noting that microduplications of 5q35.2–q35.3 comprising the NSD1 gene locus have been described in rare patients with a clinically reversed Sotos syndrome." (PMID 36230787, 2022). "The deletion of this region, including the NSD1 gene, results in macrocephaly, one of the phenotypes of the Sotos syndrome, while the duplication leads to a microcephalic phenotype, likely due to gene dosage effect." (PMID 36553552, 2022). "Sotos syndrome is due to heterozygous mutations in NSD1, a transcription coregulator gene, encoding the nuclear receptor binding SET domain protein 1 with histone methyltransferase function." (PMID 35096710, 2021). "This NSD1+/− DNA methylation signature encompasses genes that function in cellular morphogenesis and neuronal differentiation reflecting cardinal features of SOTOS syndrome." (PMID 34575025, 2021). "About 9% of individuals with Sotos syndrome of European ancestry and ~50% of those of Japanese ancestry have a specific deletion of the chromosomal region flanking NSD1 gene." (PMID 33194904, 2020). "Variants in SHANK3 can accompany Phelan–McDermid syndrome; PTEN, Cowden syndrome; NSD1, Sotos syndrome; and RAI1, Smith–Magenis syndrome." (PMID 32477112, 2020). "Through conventional genetic evaluations, germline variants were identified first, such as NF1 for neurofibromatosis and NSD1 for Sotos syndrome." (PMID 32778138, 2020). "For example, disruptions in the NSD1 enzyme can lead to several illnesses, including Sotos syndrome and Wolf–Hirschhorn syndrome, as well as gliomas, neuroblastomas and AML cancers." (PMID 32153656, 2020). "A high level of Meis1 transcript has also been seen in the lymphoblastoid cells of patients with Sotos syndrome as a result of NSD1 silencing." (PMID 33402862, 2020).